FHIT (fragile histidine triad diadenosine triphosphatase)
Diseases named in the same sentence as FHIT in open-access papers (continued):
Sharing a sentence is not in itself a finding about the gene and the disease.
tumor (continued). "FHIT has been reported to be frequently methylated in tumor cells of various human cancers." (PMID 34092254, 2021). "FHIT is a tumor suppressor acting as genome caretaker by regulating cellular DNA repair." (PMID 34092254, 2021). "On the basis of genetic evidence, it has been postulated that the FHIT protein may function as tumor suppressor, implying a role for the FHIT protein in carcinogenesis." (PMID 34901149, 2021). "The functional domains of FHIT involved in tumor inhibition was interpreted." (PMID 31089360, 2019). "LIN28A and FHIT were found overexpressed in all examined tumor types." (PMID 28423547, 2017). "Moreover, recent studies have found that FHIT can also function as the tumor suppressor by inhibiting EMT." (PMID 28036263, 2017). "FHIT (fragile histine triad) acts as diadenosine P1, P3-bis (5'-adenosyl)-triphosphate adenylohydrolase involved in purine metabolism, and induces apoptosis as a tumor suppressor." (PMID 29296239, 2017). "Moreover, FHIT overexpression driven in vivo through recombinant viral vectors, prevented tumor development in Fhit knock-out mice." (PMID 27166255, 2016). "Fragile histidine triad (FHIT) is a recently identified candidate tumour suppressor gene, which is located on the most active site of the human genome (position 3P14.2) and studies demonstrated that the expression of FHIT is reduced or absent in various malignant tumours." (PMID 25436004, 2015). "FHIT has been proven to regulate cell cycle, cell apoptosis and cell proliferation of tumor cells." (PMID 25875960, 2015). "While the FRA3B locus is highly vulnerable to DNA damage due to replication stress, the FHIT protein, paradoxically, is a tumor suppressor and genome caretaker that modulates genome stability, oxidative stress and level of DNA damage that accumulates beginning in precancerous lesions." (PMID 24901304, 2014). "The expression of mir-29 family members in lung cancer cell lines restored normal patterns of DNA methylation, inducing reexpression of tumor suppressor genes such as FHIT and WWOX that were previously silenced by methylation, thereby inhibiting tumorigenesis in vitro and in vivo." (PMID 25309923, 2014). "Furthermore, viral-mediated FHIT gene therapy inhibits tumor development and induces caspase-dependent apoptosis." (PMID 24901304, 2014). "FHIT is a tumor suppressor, appearing necessary for DNA damage response." (PMID 25478860, 2014). "Taken together, the data demonstrated that tumor stage 3, moderately differentiated tumors, presence of lymphatic invasion and absence of metastasis were more frequently observed in tumors with mutated Kras and methylated RASSF1A, FHIT and MGMT genes." (PMID 23573237, 2013). "By promoting the downregulation of the DNA methyltransferases 3A and B (DNMT3A and 3B), miR-29 induces re-expression of methylation-silenced tumor suppressor genes, such as the fragile histidine triad protein (FHIT) and the WW domain containing oxidoreductase (WWOX)." (PMID 24275848, 2013). "Overall, tumor stage 3, moderately differentiated tumors, presence of lymphatic invasion and absence of metastasis was more frequently observed in tumors with mutated Kras and/or methylated RASSF1A, FHIT and MGMT genes." (PMID 23573237, 2013). "Two tumor suppressor genes, FHIT and WWOX, are associated with FRA3B and FRA16D, respectively." (PMID 23109895, 2012). "Additionally, Fhit suppresses tumourigenicity in cancer cell lines which implies conclusively that FHIT is a bona fide tumour suppressor gene." (PMID 22295218, 2011). "Moreover, remarkably, it significantly upregulates the tumour-suppressor genes (FHIT, RASSF1, and VHL) that are known to be downregulated in NSCLC." (PMID 20736951, 2010). "Moreover, we show that u-PAR, VEGFC, and HIF1α, among other targets, are being downregulated, and the tumour-suppressor genes FHIT, RASSF1, and VHL are upregulated upon Enz treatment." (PMID 20736951, 2010).
tumor (continued). "It is evident that the expression level of FHIT decreases while tumor malignancy increases." (PMID 18366613, 2008). "Four tumor specimens showed deletions spanning the FHIT locus." (PMID 16895604, 2006). "Alterations of the FHIT gene occur early in tumour development, particularly in cancers related to environmental carcinogens, raising the possibility that carcinogen-induced alterations of WWOX gene are also an early event in the process of hepatocarcinogenesis." (PMID 15266310, 2004). "The results indicated that FHIT gene alterations could easily be detected by immunohistochemical analysis of tumour specimens." (PMID 12865924, 2003). "The FHIT (fragile histidine triad) gene on chromosome 3p14.2 is a candidate tumour suppressor gene." (PMID 11461085, 2001). "In addition to other members of the PCDH family, PCDHGB7 is closely related to proteins such as Protocadherin Fat 1(FAT1), mutL homolog 1(MLH1), and fragile histidine triad diadenosine triphosphatase (FHIT), which have been shown to be involved in DNA mismatch repair and related to tumor stemness." (PMID 39949775, 2025). "Some studies have shown that FHIT-Ap3A may inhibit tumor activity." (PMID 37372369, 2023). "Moreover, recent studies have found that FHIT can also function as a tumor suppressor by inhibiting the epithelial-mesenchymal transition (EMT) and that loss or aberrant transcripts of FHIT may be associated with carcinogenesis." (PMID 32375395, 2020). "Therefore, FHIT can be considered as a tumor suppressor, and its inactivation could contribute tumor progression and poor prognosis." (PMID 26796853, 2016). "Apart from its pro-apoptotic, growth inhibitory, and anti-angiogenic properties, this could be, at least in part, due to downregulating tumour progression and invasion-related genes (u-PAR, HIF1α, and VEGFC) and upregulating NSCLC tumour-related suppressor genes (FHIT, RASSF1, and VHL) by Enz." (PMID 20736951, 2010). "Whereas the HMGA2::MSRB3 and HMGA2::FHIT fusions were described in previous studies, the remaining detected fusion partners such as ARID2 or IFNG-AS1 are novel in this tumor type." (PMID 40033554, 2025). "Alteration of mRNA levels of CDH1, FHIT, PTEN, and TTPAL genes in tumor tissues was determined compared to control tissues." (PMID 36161592, 2022). "While the mRNA levels of CDH1 decreased, the mRNA level of the FHIT and TTPAL genes increased in the tumor tissues." (PMID 36161592, 2022). "We analysed the expression of mRNAs for CDH1, PTEN, FHIT, and TTPAL by real-time PCR and observed downregulation of CDH1 and upregulation of FHIT and TTPAL in the tumor tissues." (PMID 36161592, 2022). "FANCD2 and FANCI are required for the maintenance of two common fragile sites’ (CFSs) loci, FRA3B and FRA16D, in which the large tumor suppressor genes FHIT and WWOX reside." (PMID 34828369, 2021). "According to these findings, FHIT expression induction and the consequent recovery of MHC-I expression on tumor cells suggests a potential immunotherapeutic strategy." (PMID 32545680, 2020). "Apart from WDR1, several other oncoproteins and tumour suppressors, such as LDHA, CLIC1, ARPC5, ZYX, RCN1, FHIT and CFTR, were identified in this study." (PMID 32601462, 2020). "This gene has been found to inhibit the proliferation of tumor cells, induce their apoptosis, and increase invasion and their susceptibility to chemotherapeutic agents; however, it has been also reported that FHIT does not act as a direct tumor suppressor gene." (PMID 32545680, 2020). "Allelic losses or hypermethylations on the 3p region has been observed more frequently in tumors with a squamous histology compared with adenocarcinoma, involving some tumor suppressor genes such as RASSF1A, FUS1, VHL, and FHIT." (PMID 28591695, 2017).
tumor (continued). "FHIT synergizes with VHL, another tumor suppressor, to protect against chemically induced lung cancer." (PMID 28811522, 2017). "Copy number alterations of MYC (8q24.21), FHIT (3p14.2), WDR60 (7q36.3), COL4A2 (13q34), NFATC1 (18q23), and NCOA3 (20q12) were analyzed in six matched tumor and normal tissue pairs (268–1, 271–1, 272–2, 301–1, 685–1 and 685–2)." (PMID 26360582, 2015). "Compared to empty vector control, FHIT-overexpressing OML1-R cells exhibited significantly less tumor growth than mice injected with mock-transfected OML1-R cells, thus confirming high tumor suppression by FHIT, in vivo." (PMID 25460508, 2015). "Among these rearrangements, 12 contained small exonal deletions, and most of the affected genes, including FHIT, CDH13, DACH1, and RBFOX1, have been reported as tumor suppressors or as deleted in cancer, suggesting their active role in tumorigenesis." (PMID 24937453, 2014). "However, we failed to observe any association between tumor grade and methylated FHIT." (PMID 23573237, 2013). "Tumor stage and metastasis correlated with presence of mutant Kras codon 12 (p-values 0.018, 0.044) and methylated RASSF1A (p-values 0.034, 0.044), FHIT (p-values 0.001, 0.047) and MGMT (p-values 0.018, 0.044) genes." (PMID 23573237, 2013). "FHIT and WWOX (the genes located within FRA3B and FRA16D respectively) have both been shown to function as tumour suppressors genes, and their inactivation have been associated with a poor clinical prognosis in cancer." (PMID 23675233, 2011). "MeDIP-qPCR and qPCR were performed to measure demethylation status and mRNA re-expression level of 7 tumor-suppressor genes (CCNA1, CHFR, FHIT, PAX1, PTEN, SFRP4, TSLC1) in Hela and Siha cells after silencing DNMT1." (PMID 21999220, 2011). "These include the FHIT and RASF1 tumor suppression genes, several forms of the TGF-β receptor, pentaerythritol tetranitrate, vascular endothelial growth factor (VEGF), and carbonic anhydrase." (PMID 24213122, 2011). "Tumour-suppressor genes VHL, RASSF1, and FHIT are downregulated in NSCLC, which are implicated in the ubiquitin ligase system, cell-cycle regulation, and apoptosis, respectively." (PMID 20736951, 2010). "Genes promoting cancer progression (u-PAR, VEGFC, and HIF1α) and tumour suppression (VHL, RASSF1, and FHIT) of NSCLC were significantly (P<0.05) down- or upregulated after Enz treatment in H460, A549, and H1299 cells, respectively." (PMID 20736951, 2010). "The two most highly breakable fragile sites, FRA3B and FRA16D, lie within the tumor suppressor genes FHIT and WWOX, respectively." (PMID 21286310, 2010). "The tumor specimens delineated as CA3 and CA4 had preferential deletions of FHIT specific exons, FHIT exon 5, and FHIT exons 3 and 4 respectively." (PMID 16895604, 2006). "A candidate tumour suppressor gene, fragile histidine triad (FHIT), was identified at chromosome 3p14.2 spanning the FRA3B common fragile site." (PMID 14760383, 2004). "The frequency of promoter hypermethylation of the tumor suppressor gene loci included in the panel was FHIT 28%, FANCF 24%, Cyclin-D2 12%, BRCA2 4%, and RUNX3 56% of the 25 tumours." (PMID 15574200, 2004). "The FHIT gene encompassing the most active common human chromosomal fragile region, FRA3B, was discovered in 1996 and proposed as a tumour suppressor gene for important human cancers." (PMID 12771912, 2003). "A consensus region found to be deleted in all the tumours with 3p deletions was defined by markers D3S1286 and D3S1295, i.e. 3p25.3-p14.3, distal to the FHIT gene." (PMID 9667647, 1998). "In tumours developed in heavy-smoking subjects, the frequency of LOH at the FHIT locus was significantly higher (P = 0.006) than in tumours from non-smoking subjects." (PMID 9662254, 1998).
tumor (continued). "Notably, the 3p chromosome change impacts over 500 genes, featuring tumor suppressors like BAP1, FHIT, VHL, PTPγ, SEMA3B, SEMA3F, TUSC2, and MLH1." (PMID 39201328, 2024). "A risk classification model based on the immunohistochemical expression of three proteins (APC, FHIT, and HER2) and five pathological parameters (tumor stage, resected nodes, margins, location, and sex) accurately separates the patients with GC into three groups." (PMID 35402221, 2022). "We recently showed that the tumor suppressor fragile histidine triad (FHIT), frequently lost in NSCLC, controls HER2 receptor activity in lung tumor cells and that tumor cells from NSCLC patients harboring a FHITlow/pHER2high phenotype are sensitive to anti-HER2 drugs." (PMID 36544755, 2022). "It is interesting to note that some of the most common CFSs, such as FRA3B and FRA16D, are encompassed by FHIT and WWOX tumor suppressor genes, respectively, suggesting that breaks at these genes could infer positive selection and growth advantage." (PMID 32785139, 2020). "Loss in FHIT and RB1 were the only well described HNSCC associated mutations detected in TADE and which were absent from both the tumor and NE, suggesting this TADE is an independent clone and not related to the tumor." (PMID 32426287, 2020). "Of note, these tumor suppressive functions of FHIT are mediated by its interacting partners rather than by its intrinsic catalytic hydrolase and/or transferase activity." (PMID 27977694, 2016). "Like FHIT, WWOX has a range of tumor-suppressing functions, affecting DNA repair and apoptosis, which identifies it as a master regulator that protects cells against genomic instability and tumor progression." (PMID 27977694, 2016). "We wanted to gain more knowledge about the expression of HMGA2-related miRNAs such as miR-30c and let-7a, and whether a correlation exists between the expression of FHIT and HMGA2, in this tumor type." (PMID 27835588, 2016). "The genes FHIT and RBM5 are suggested as tumor suppressor genes." (PMID 25860936, 2015). "Tumor samples in this cohort with normal FHIT expression do not exhibit APOBEC hypermutation, despite having high APOBEC3B expression." (PMID 25401976, 2015). "Although FHIT is lower in ccRCC compared to normal kidney, higher FHIT levels in higher grade and stage tumours do not support the tumour suppressor function of FHIT." (PMID 26448938, 2015). "The aim of this study was to describe the morphological characteristics and the DNA methylation status of the CDKN2A,CDH1, ATM, FHIT and RAR- genes in the central and peripheral part of the tumor and the surgical margin and evaluate their prognostic significance." (PMID 24782031, 2014). "These strongly remind us that FHIT may affect downstream gene through the PI3K/Akt pathway and thus plays a role as tumor suppressor." (PMID 24757411, 2014). "In this regard, the enforced expression of miR-29 in lung cancer cell lines led to reduced global DNA methylation, induced re-expression of methylation-silenced tumor suppressor genes, such as FHIT and WWOX, and inhibited tumor cell proliferation in vitro and tumor growth in vivo." (PMID 24275848, 2013). "An increase in the amount of FHIT protein level in non-neoplastic skin versus tumour samples was observed; moreover FHIT expression levels were lower in sarcoid cell lines compared to E-DERM." (PMID 22424615, 2012). "The FHIT gene is often involved in deletions which map specifically to the fragile site region in various types of cancer, and deletion of WWOX is also frequently observed in tumor cells." (PMID 21286310, 2010). "Carcinoma cell lines and primary tumours exhibit hemizygous or homozygous deletion with end points within fragile regions of the human genome, particularly within the most active common fragile site, FRA3B, encompassed by the FHIT gene." (PMID 19352382, 2009).
tumor (continued). "Tumor behaviour and growth are considerably influenced by the expressions of two types of genes in the human genome: the cell proliferating genes (for instance, Ki-67 and PCNA) and tumor suppressor genes (for example FHIT)." (PMID 18366613, 2008). "Known tumour suppressor genes, although not included in this list, were noted as downregulated in the array analysis for example, the FHIT (LBFC=−5.39) at 3p14.2; ST7 (LBFC=−2.95) at 7q31 or CLDN23 (LBFC=−4.58) at 8p23.1." (PMID 17406368, 2007). "Our own result indicates that methylated alleles were found in all tumor and normal DNA i.e. FHIT methylation was not tumor-specific." (PMID 16928264, 2006). "This study describes the value of an innovative approach using an MLPA assay specifically designed to scan the exon intragenic composition of the FHIT and WWOX genes involved at fragile sites, here evaluated in the setting of ESCC South African cell lines and primary tumor specimens." (PMID 16895604, 2006). "Simultaneous scanning of FHIT and WWOX exons in the context of early tumorigenesis and tumor progression, may help clarify the mechanistic events related to cancer development which are not revealed by imuno histochemistry assays." (PMID 16895604, 2006). "FHIT loss, with or without WWOX loss, has been shown to correlate positively with tumor invasiveness and prognosis in several cancers (breast, pancreas, gastric cancers)." (PMID 16895604, 2006). "Relatives (not shown) and absolute peak heights comparison of tumor to control specimen, showed FHIT exons 4 and 5 deletion in cell line WHCO5 (ratio of 0.55), compatible with a hemizygous deletion." (PMID 16895604, 2006). "Six tumor specimens showed an amplification profile comparable to that of the mean reference control with no significant exon deletions of FHIT or WWOX, (results not shown)." (PMID 16895604, 2006). "The genes APC, MGMT; ER, GSTP1, DAPK, RARβ, FHIT and p16 were evaluated pre and post-treatment for DNA promoter methylation and gene expression by MSP (Methylation-Specific PCR) and RT-PCR respectively in each of the tumor samples." (PMID 15862127, 2005). "Out of 17, 13 (76.5%) tumours with negative Fhit expression demonstrated LOH at the FHIT locus, whereas six out of 11 (54.5%) tumours with positive Fhit expression demonstrated LOH at D3S1766." (PMID 15150628, 2004). "While in our study Fhit inactivation does not seem to be a common event in CDC, an involvement of the FHIT gene in tumorigenesis of this rare tumor cannot be excluded." (PMID 15357873, 2004). "6% (3/45) of tumours evinced no detectable expression of any FHIT transcript and a further 12% (6/45) produced only the normal full length transcripts." (PMID 10555761, 1999). "We conclude that the FHIT gene and other uncharacterized tumour-suppressor genes at 3p14.2 are unlikely to be involved in the pathogenesis of acute leukaemia or progression of CML from chronic phase to blast crisis." (PMID 9744498, 1998). "Based on these pathways, the first tumor may have developed by the former mechanism and the remaining three tumors by the latter mechanism, though the FHIT inactivation was not examined." (PMID 38615286, 2024). "Moreover, FHIT protein inhibits cell proliferation and induces apoptosis as a tumor suppressor, which is independent of its hydrolase activity." (PMID 29296239, 2017). "There is a significant correlation between low or absence of FHIT protein expression and low grade and early stage ccRCC tumours indicating that LOH of FHIT may play a role in early tumour development." (PMID 26448938, 2015). "As a result of inactivation, FHIT protein expression is low or absent in most ccRCC tumours." (PMID 26448938, 2015).